GUCD1 (guanylyl cyclase domain containing 1)
Synonyms: C22orf13; LLN4; MGC1842
Tractability: PROTAC: ubiquitination databases record sites on it.
Gene: Protein-coding gene on chromosome 22 (24,540,423 to 24,555,935, reverse strand). Ensembl gene ENSG00000138867.
Subcellular location (Human Protein Atlas): Nucleoplasm
Gene Ontology:
Molecular function: protein binding
Biological process: liver regeneration; response to cAMP
Genetic constraint (gnomAD): Loss-of-function variants: 16 observed, 24.42 expected, observed/expected ratio (o/e) 0.66, 90% interval 0.44 to 1. The upper end of that interval is the gene's LOEUF score, 1, which puts it in group 4 of 6, group 1 being the genes least tolerant of losing a copy. Missense variants: 272 observed, 292.11 expected, observed/expected ratio (o/e) 0.93, 90% interval 0.84 to 1.03. Synonymous variants: 129 observed, 120.75 expected, observed/expected ratio (o/e) 1.07, 90% interval 0.93 to 1.24.
Homologues: Orthologues: chimpanzee GUCD1 (96% identical), mouse Gucd1 (96% identical), macaque GUCD1 (95% identical), dog GUCD1 (95% identical), pig GUCD1 (95% identical), rat Gucd1 (94% identical), guinea pig GUCD1 (92% identical), rabbit GUCD1 (90% identical), tropical clawed frog gucd1 (71% identical), zebrafish gucd1 (66% identical), Drosophila melanogaster CG13760 (36% identical).
Diseases named in the same sentence as GUCD1 in open-access papers:
GUCD1 is named in the same sentence as 4 diseases in open-access papers, as found by Europe PMC text mining. Sharing a sentence is not in itself a finding about the gene and the disease. The quoted sentences say what the papers report.
hepatocellular carcinoma (1 paper, 2022). A malignant tumor that arises from hepatocytes. "Furthermore, exosomal circ-0003258 promotes hepatocellular carcinoma progression via miR-29a-3p/GUCD1 Axis." (PMID 34986849, 2022).
Sepsis (1 paper, 2025). Sepsis is defined as life-threatening organ dysfunction caused by a dysregulated host response to infection. "Notably, TNFSF10, GUCD1, and PLVAP show strong associations with pathways sepsis-relevant sepsis development." (PMID 40362669, 2025).
cancer (2 papers, 2021 to 2023). A tumor composed of atypical neoplastic, often pleomorphic cells that invade other tissues. "CAGE-seq detects altered transcription initiation patterns in cancer as demonstrated by the promoter of GUCD1 (encoding guanylyl cyclase domain containing 1), a gene associated with enhanced cell proliferation and invasion of cancer cells." (PMID 37996663, 2023).
tumor (2 papers, 2023 to 2024). "Human ortholog, GUCD1 (LLN4), interacts with NEDD4-1 affecting tumor suppressors and lacks the domain providing the cyclase function described for GC1." (PMID 37164157, 2023).